CD44 (CD44 molecule (IN blood group))
Diseases named in the same sentence as CD44 in open-access papers (continued):
Sharing a sentence is not in itself a finding about the gene and the disease.
breast carcinoma (continued). "Stable NRF1 overexpressing MCF10A cells, after treatment with a carcinogenic regimen of E2, were grown as mammospheres in B27 medium then flow cell sorted for the breast cancer stem cell signature CD24−/CD44+." (PMID 30486409, 2018). "As the hetero-dimerization of HER2 and EGFR drives breast cancer progression and cancer stemness, we then observed the expression of CD44, HER2, and EGFR." (PMID 29464036, 2018). "Overexpression of Foxp3 in two breast cancer cell lines downregulated both mRNA and protein expression levels of CD44." (PMID 29747682, 2018). "An animal study looking at CD44 overexpression as stemness in breast cancer, found these conjugates were able to identify CD44+ cells where T2 signal was decreased by the magnetic nanoclusters in contrast with other tissue." (PMID 30149561, 2018). "We observed polarisation of ezrin and CD44 in cells from pleural effusion (PE) or ascitic effusion (AE) of pancreatic and breast cancer patients showing that sc polarity occurs in human patients." (PMID 29491397, 2018). "Two well-known breast-cancer stem-cell markers, CD44 and ALDH1 family member A1 (ALDH1A1), were examined." (PMID 30513573, 2018). "According to our results, HA-FeOOH@PPy NRs have shown great binding capacities with CD44-positive breast cancers, and HA-FeOOH@PPy NRs-mediated PTT has led to a selective destruction of CD44-positive breast cancer cells." (PMID 29891947, 2018). "CD44 expression is also linked to β-catenin and AKT pathways in breast cancer and cervical cancer cells." (PMID 29747682, 2018). "In nasopharyngeal carcinoma and breast cancer, CD44 activates STAT3 and promotes the maintenance of a stem cell–like subpopulation." (PMID 30271576, 2018). "DNA aptamers that specifically bound to CD44 exon v10 inhibited the migration of breast cancer cells." (PMID 29747682, 2018). "Transient knock-down of Foxp3 from breast cancer cell lines upregulated both mRNA and protein level of CD44, indicating that Foxp3 is a negative regulator of CD44." (PMID 29747682, 2018). "In this study, first, we aimed to establish a close correlation between CD44 and ERα expression in ER+ breast cancer cells with oestrogen stimulation or the development of paclitaxel resistance." (PMID 30179299, 2018). "Retroviral-mediated CD44 knock-down decreased cell proliferation, migration, and invasion of breast cancer cells." (PMID 29747682, 2018). "Experimental evidence shows that hyaluronan–CD44 interaction intensifies the proliferation, migration, and invasion of breast cancer cells." (PMID 29483847, 2018). "mRNA levels of MMP2 and MMP9 were elevated in CD44 positive breast cancer cells compared to CD44-negative cells." (PMID 29747682, 2018). "The CD24+/CD44+ subpopulation upon carcinogenic E2 treatment produced as many as seven different downstream breast cancer progenitor cell subpopulations." (PMID 30486409, 2018). "A short while later, the same authors developed an ESTA-based approach to block E-selectin-supported hematogenous metastases of ER−/CD44+ breast cancer cells by preventing their adhesion to E-selectin-expressing premetastatic endothelial niche." (PMID 30428522, 2018). "This is in agreement with the notion that IBC down‐regulates CD44 expression by the ERα pathway to sensitize breast cancer cells to paclitaxel." (PMID 30179299, 2018). "Although CD44 and CD133 have been used to enrich CSCs from human breast cancer, colon cancer, and liver cancer, CD44 was detected on the mouse breast EMT6, colon CT26, and liver Hepa1-6 CCs." (PMID 29755667, 2018). "Our studies thus provide further proof for an interaction between OPN and CD44 that helps aggressive breast cancer cells to facilitate migration, spontaneous dissemination, and formation of metastatic nodules." (PMID 30038419, 2018).
breast carcinoma (continued). "Recently, Li and colleagues reported that tumorigenic breast cancer cells expressing CD44+/CD24-/low have primary resistance to conventional chemotherapy and accordingly their proportion increases after chemotherapy." (PMID 29416796, 2018). "In breast cancer tissue, we identified that AR expression was positively correlated with let-7a expression, but negatively with CD44+/CD24-/low phenotype of cancer cells." (PMID 29423076, 2018). "In an inflammatory microenvironment, COX-2 stimulates the development of breast cancer stem cells, and the proliferation of CD44+ stem-like cells in gastric cancer is cooperatively stimulated by COX-2/PGE2-mediated signaling." (PMID 30402042, 2018). "Experimental evidence shows that hyaluronan–CD44 interaction intensifies the proliferation, migration, invasion, tumor angiogenesis, and patient survival of breast cancer cells." (PMID 29483847, 2018). "Our current in vivo results are consistent with recent findings in MCF7 and MDA-MB-468 cells, two human breast cancer cell lines in culture, which showed significant reductions in the CD44(+)/CD24(-/low) CSC population, after treatment with doxycycline." (PMID 30364293, 2018). "In summary, a gain in NRF1 expression and/or treatment with E2 led to reprogramming of normal breast epithelial cells to acquire the breast cancer stem cell signature CD24−/CD44+." (PMID 30486409, 2018). "In conclusion, in ER-positive early breast cancer, the incidences of CD44+/CD24- and ALDH1-positivity by IHC, which are potential breast cancer stem cell markers, were very low." (PMID 29416796, 2018). "Although CD44 and CD24 expression is a poor prognostic marker for different tumours including breast cancer, the role of CD44 and CD24 in paclitaxel resistance of breast cancer cells stimulated by E2 needs further study." (PMID 30179299, 2018). "The expression of serglycin and CD44 core proteins enhanced in breast cancer cells and CS-E subunit attaches to CD44 to promote and regulate breast cancer progression." (PMID 29747682, 2018). "Experimental evidences show that hyaluronan–CD44 interaction intensifies the proliferation, migration, and invasion of breast cancer cells." (PMID 29483847, 2018). "Our previous work showed that breast cancer stem cells express CD44+CD24− or ALDH+, and that these two markers isolate distinct populations of mesenchymal-like and epithelial-like cells, respectively." (PMID 29606612, 2018). "We recently demonstrated that SIRT7 deficiency activates TGF-β signaling, enhances EMT and promotes lung metastasis, and induces mesenchymal-like CSCs marked with CD44+CD24- in breast cancers, providing a proof of concept of aging-promoted CSC induction." (PMID 30038266, 2018). "In breast cancer, a shift in CD44 expression from CD44v to CD44s occurs during EMT, and this isoform switching is essential for cells to undergo EMT." (PMID 30042817, 2018). "At first glance, our data seems to be in contrast with current assertions that the CD44+/CD24-/low subpopulation with tumor-initiating properties is positively correlated with distant metastasis in breast cancer." (PMID 29416796, 2018). "Conversely, we observed an inverse correlation between the number of CD44-positive breast cancer cells and the BOLCs (p < 0.0001, R2 0.627)." (PMID 30327566, 2018). "After radiation, CD44+/CD24− BCSCs isolated from established breast cancer cell lines and primary culture of patient breast cancer cells presented high ATM signaling activity, and treatment with an ATM inhibitor resensitized these cells to radiation." (PMID 30200262, 2018). "The positive association between the CD44+/CD24-/low presence and AR expression was more obvious in ER+ breast cancers, which was consistent with our in vitro results." (PMID 29423076, 2018). "Conversely, we observed an inverse correlation between the number of CD44-positive breast cancer cells and the BOLCs." (PMID 30327566, 2018).
breast carcinoma (continued). "Breast cancers are also hierarchically organized and driven by cancer stem cells characterized by CD44+CD24low/− or aldehyde dehydrogenase (ALDH) expression." (PMID 29606612, 2018). "Gemini vitamin D decreased CD44 protein level, inhibited the invasion of the basal-like human breast cancer cells, and reduced tumor size in an orthotopic mice model." (PMID 29747682, 2018). "Their identification from tumor samples and mammary cancer cell lines has been based mainly on CD44, CD24, and ALDH1 phenotypes." (PMID 30092754, 2018). "In mammary tumor cell lines downregulation of CD44 reduced and overexpression of CD44-ICD enhanced the expression of the stemness factors Nanog, Sox2 and Oct4." (PMID 30540779, 2018). "Accordingly, it was recently reported that CD44 supported adhesion of basal-like breast cancer cell to endothelium and fibronectin in an integrin α5β1-dependent manner." (PMID 29371972, 2017). "In breast cancer, putative cancer stem cells (CSCs) with CD44 positive phenotype constitutes 12–35% of the tumor cells." (PMID 29187162, 2017). "Since WNT5A inhibits breast cancer cell migration and invasion in part by reducing the levels of CD44, we have explored if WNT5A signaling regulates the expression of this protein also in prostate cancer tissue." (PMID 28886116, 2017). "For example, CD44 protects chronic lymphocytic leukemia cells from spontaneous and induced cell death by increasing expression of the MCL-1 pro-survival protein, while CD44 activation in breast cancer cells induces c-Jun mediated survival." (PMID 28380429, 2017). "A similar effect was observed in the case of the maintenance of CD44+CD24− breast cancer cells by LDR." (PMID 28240233, 2017). "Recent observations have shown that CD44 intracellular domain (CD44-ICD) is related to the metastatic potential of breast cancer cells." (PMID 28326306, 2017). "To examine the labeling specificity of the SERS conjugates, we used darkfield microscopy to image various breast cancer cell lineages stained with HER2 or CD44 conjugated SERS NPs after fixation." (PMID 28667313, 2017). "Evidence of the breast CSCs resistance is supported by a study in which tumor biopsies taken from patients with breast cancer during the 12-week chemotherapy treatment conducted increased CSC markers (CD44+/CD24-/low and MFSE)." (PMID 28245823, 2017). "Human breast cancer cells with CD44+/CD24−/EpCAM+ expression markers and/or possessing ALDH1 enzyme activity are recognized as CSCs and are responsible for maintaining tumor growth." (PMID 29069872, 2017). "Marotta and the colleagues reported that the JAK2/STAT3 signaling pathway was required for growth of CD44+CD24− stem cell-like breast cancer cells." (PMID 28591704, 2017). "On the other hand, rhBMP-2 upregulated the expression of CD44 proteins and promoted the stemness of breast cancer cells." (PMID 28725489, 2017). "Previous works identified that CD44 is an E-selectin ligand on several different types of cells, such as HSPCs, neutrophils, mouse Th1 cells, breast cancer cells, colon carcinoma cells, and melanoma." (PMID 28515724, 2017). "Lower expression of CD24, CD44, ALDH1 and EpCAM is linked with better prognosis of breast carcinoma in patients." (PMID 28524540, 2017). "Tumorigenic CD44+CD24−/low cells are also detected in metastatic pleural fluid in breast cancer patients and breast CSC phenotypes are found in bone marrow." (PMID 27974675, 2017). "CD44 expressed on breast cancer cells serves as a major ligand for endothelial cell surface located E-selectin and mediates CTC adhesion to the endothelium." (PMID 28785589, 2017). "Previous studies have shown that STAT3 can function as a modulator for CD44 expression in aggressive breast cancer cells and promote the CSC phenotype." (PMID 29036915, 2017).
breast carcinoma (continued). "CD49f and CD44, a stem cell marker, are transcriptionally upregulated by Y-box binding protein-1 (YB-1) in breast cancer cells, enhancing the stem-like properties of these cells, which include self-renewal, colony forming efficiency and drug resistance." (PMID 27343550, 2017). "It has been reported that breast cancer cells with the CD44+CD24– phenotype and stem-cell–like features are highly resistant to cancer therapies." (PMID 28240233, 2017). "In this study, 19 public datasets were enrolled to assess the correlation between the mRNA levels of DACH1 and CD44 and the survival performance of breast cancer patients." (PMID 28659634, 2017). "The CD44+/CD24− phenotype is among the most widely studied biomarkers for breast cancer stem cells (CSC), but the clinical impact of these reported CSC biomarkers remains controversial." (PMID 28418843, 2017). "DACH1 was majorly found in nucleus and CD44 was mostly detected on the membrane of breast cancer cells." (PMID 28659634, 2017). "Molecules 1 and 7 possessed a highly potent CSC inhibitory activity to MDA-MB-231 breast cancer cell line and displayed similar effects in reducing the percentage of CD44+/CD24− breast CSC subpopulation at 1 μM." (PMID 28718836, 2017). "Another study reported an oligo-HA-induced physical interaction between the main HA receptor CD44 with TLR2 and TLR4 causing pro-inflammatory cytokine and chemokine production in breast cancer cells via NF-κB transcription." (PMID 29062810, 2017). "We found that CD44+Fbs promoted breast cancer cell survival and paclitaxel resistance and inhibited paclitaxel‐induced apoptosis." (PMID 28523716, 2017). "PTPRD knockdown also increased the CD44+/CD24− breast cancer stem cell (BCSC) population and the expression of the stem cell markers ALDH1 and OCT4." (PMID 29228728, 2017). "In conclusion, this study shows that bone-derived OPN promotes the migration of breast cancer cells and contributes to maintaining the stem-like behavior of breast cancer cells through interactions with CD44 and RGD-dependent integrins." (PMID 28498874, 2017). "Using Transwell coculture system, we found that breast cancer cell proliferation was enhanced in the presence of CD44+Fbs than CD44−Fbs." (PMID 28523716, 2017). "Various breast cancer cells show abnormal expression of CD44 including heterogeneously expressing CD44 isoforms." (PMID 28326306, 2017). "Our data showed that ACEA has an inhibitory effect on CD44+/CD24-breast cancer stem cell and their parental cell invasion but AM251 increases invasiveness." (PMID 29552056, 2017). "On the other hand, studies showed that STAT3 signaling is required for the growth of CD44+/CD24− stem cell-like breast cancer cells." (PMID 29228728, 2017). "Altogether, TRAP promotes metastasis-related cell properties in MDA-MB-231 breast cancer cells via TGFβ2/TβR and CD44, thereby identifying a potential signaling mechanism associated to TRAP action in breast cancer cells." (PMID 28915803, 2017). "For example, YB-1 increases the expression of stem cell marker proteins, such as CD44 and CD49f, in breast cancer." (PMID 27911878, 2017). "Studies have shown that breast cancer stem cells (BCSCs, marked as CD44+/CD24−) promote tumor progression and exhibit enhanced invasive properties to favor distant metastasis in patients." (PMID 28725489, 2017). "HA and CD44 co-localize in the bone marrow sinusoidal epithelium, which is a site of metastasis of breast cancer." (PMID 28326306, 2017). "The isolation of CSCs from oral cancers has mainly been performed with the CD44 marker that was initially used to isolate breast cancer CSCs." (PMID 29211293, 2017). "We demonstrate that bone-derived OPN promotes the migration and stem-like properties of breast cancer cells via the cell surface receptor CD44 and RGD-dependent cell surface integrins, resulting in activation of WNK-1 and PRAS40." (PMID 28498874, 2017).
breast carcinoma (continued). "This is the first time that CD74 and CD44 colocalization has been quantified in breast cancer cells using a non-invasive and validated bioimaging procedure." (PMID 29190904, 2017). "Our results demonstrated that DACH1 was a promising biomarker predictive of better clinical outcomes, while CD44 was an adverse factor for the survival performance of breast cancer patients." (PMID 28659634, 2017). "Both putative breast cancer stem cell subpopulations expressing the ALDH1 or the CD44+CD24-/low phenotype, showed similar sphere formation efficiency." (PMID 28423035, 2017). "A third study showed that CD44+CD24-/low cells were concentrated in breast cancers invasive protrusions." (PMID 28052035, 2017). "Here, we found that p62 expression was elevated in breast cancer stem cells (BCSCs), including CD44+CD24− fractions, mammospheres, ALDH1+ populations and side population cells." (PMID 27345399, 2017). "Stem-like cells of ALDH1 or CD44 positive phenotype featured to be enriched in patients with progressed breast cancer, indicating that the greater proportion of stem cells was correlated to advanced tumor stages." (PMID 29262559, 2017). "In our method, CD44+/CD24− cells were isolated from breast cancer cells (SUM149) by first mixing with anti-CD24-antibody-coated nonmagnetic beads before mixing with anti-CD44-antibody-coated magnetic beads." (PMID 28074882, 2017). "Tumor-initiating cells (TICs) are cancer cells endowed with self-renewal, multi-lineage differentiation, increased chemo-resistance, and in breast cancers the CD44+/CD24-/ALDH1+ phenotype." (PMID 28052035, 2017). "The first CSCs to be discovered in solid tumors were tumorigenic CD44+/CD24−/low breast cancer cells in severe combined immunodeficiency mice." (PMID 28423353, 2017). "It was shown breast cancer cells cocultured with CD44+Fbs became more resistance to paclitaxel and lower apoptosis rates than cells cocultured with CD44−Fbs." (PMID 28523716, 2017). "Based on the in vitro and in vivo results, we have established an integrated mechanism by which rhBMP-2 induces EMT and stemness of breast cancer cells via the Rb and CD44 signaling pathways, which then contribute to breast cancer metastasis." (PMID 28725489, 2017). "The MDA-MB-231 and HS-578T cell lines possess the highest number of CD44+CD24−/low cells while MCF-7 and T-47D luminal as well as MDA-MB-468 basal-like breast cancer cell line are characterized by very low number of CD44+CD24−/low cells." (PMID 27845900, 2017). "Recently, ESRP1 has been reported to act as a tumor suppressor by negatively regulating epithelial-to-mesenchymal transition (EMT) and the metastatic potential of human breast cancer cell lines, via the splicing of different isoforms of CD44 or EXO70." (PMID 28975893, 2017). "We first accessed the expression of CD24,CD44v and total CD44 in breast cancer clinical samples through immunofluorescence staining and observed both CD44v+ CSCs (CD24−/CD44+/CD44v+) and CD44v− CSCs (CD24-/CD44+/CD44v−) in tumor tissues." (PMID 28300837, 2017). "It has been reported that BCSCs show a higher rate of bone metastases, compared with parental breast cancer cell line, expressed higher levels of CD44, CXCR4, and osteopontin markers." (PMID 29099748, 2017). "Development of breast cancer stem-like cells are associated with expression of low levels of CD24, high levels of CD44, aldehyde dehydrogenase, and the IL8-binding chemokine receptor CXCR1." (PMID 28785589, 2017). "In summary, this is the first study demonstrating that BMP-2 promotes EMT and breast cancer stemness via Rb and CD44 signaling pathways." (PMID 28725489, 2017). "The mechanism underlying the different expression of CD44/CD24 and ALDH1 in breast cancer has yet to be found." (PMID 29062075, 2017). "Overexpressed in breast cancer, Y-box binding protein 1 (YB-1) can be specifically bound to the A/C-rich pre-mRNA regions of CD44 to stimulate the expression of the alternative Exon V4." (PMID 28881705, 2017).